GSTM5 (glutathione S-transferase mu 5)
Diseases named in the same sentence as GSTM5 in open-access papers (continued):
Sharing a sentence is not in itself a finding about the gene and the disease.
type 2 diabetes mellitus (1 paper, 2015). A type of diabetes mellitus that is characterized by insulin resistance or desensitization and increased blood glucose levels. "Eleven genes in the Glutathione metabolism pathway (Gpx7, Gss, Gsta3, Gstm2, Gstm5, Gstm7, Gsto1, Gstp1, Gstt1, Gstt2 and Mgst2) were observed in type 2 diabetes mellitus." (PMID 25788156, 2015).
urothelial carcinoma (1 paper, 2016). A malignant neoplasm derived from the transitional epithelium of the urinary tract (urinary bladder, ureter, urethra, or renal pelvis). "One is the GSTM1 gene which is down-regulated in mice bladder carcinogenesis and is usually deleted in human urothelial carcinoma, while the other is the GSTM5 gene, which is inactivated by DNA CpG methylation." (PMID 27404495, 2016).
Uterine leiomyoma (1 paper, 2013). The presence of a leiomyoma of the uterus. "On the other hand, gene expression of GSTM5 was decreased in uterine leiomyomas." (PMID 23818951, 2013).
cancer (14 papers, 2010 to 2026). A tumor composed of atypical neoplastic, often pleomorphic cells that invade other tissues. "The analysis showed that low GSTM5 expression was positively associated with related to DNA repair pathways which may suggest that GSTM5 is involved in LUAD progression through these cancer-associated pathways." (PMID 35729618, 2022). "Methylation-specific PCR results showed that the GSTM5 gene was hyper-methylated in LUAD cancer cell line, suggesting that GSTM5 gene silencing in cancer cell may be associated with the hypermethylation of its promoter." (PMID 35729618, 2022). "NCBI Entrez gene database reported that: CHEK2 is a cell cycle checkpoint regulator and putative tumor suppressor, and associated with GBM; GSTM5 was reported to be involved in cancer, BCL11A is a proto-oncogene, and FN1 is involved in tumor metastasis and angiogenesis." (PMID 21114830, 2010). "In addition, other published reports have indicated an association between GSTM5 and cancers." (PMID 33802702, 2021). "Regarding GSTM5, its expression has been shown to be significantly downregulated in various cancer types, including bladder, ovarian, and lung cancer." (PMID 40868127, 2025). "Despite the established relevance of GSTM5 in cancer, its specific function in PC and treatment response remains poorly understood." (PMID 40868127, 2025). "Using the Illumina Methylation 450k Beadchip, we compared the methylation status of 10 CpG sites in GSTM5 DNA between cancer tissues and their adjacent normal samples." (PMID 35729618, 2022). "Differences between GSTM5 DNA methylation levels at various cancer stages were also analyzed, and the results also indicated a significant difference." (PMID 33802702, 2021). "Overexpression of GSTM5 was found to decrease cancer cell proliferation and migration by decreasing cellular GSH levels." (PMID 33802702, 2021). "Taken together, these data suggest that the GSTM5-induced suppression of cancer cell proliferation and migration were reversed by intracellular GSH supplementation." (PMID 33802702, 2021). "Notably, treatment with demethylating agents such as 5-Aza-CdR has been shown to restore GSTM5 expression and inhibit tumor cell proliferation and migration, reinforcing the potential therapeutic value of targeting DNA methylation in cancer." (PMID 40868127, 2025). "To date, several studies have reported a correlation between GSTM5 and cancer, though the direct effects of GSTM5 on tumor cells remain unclear." (PMID 33802702, 2021). "Therefore, the influence of GSTM5 on doxorubicin sensitivity is different between diverse cancer cells." (PMID 33802702, 2021). "However, the exact mechanistic role of GSTM5 in cancer remains elusive." (PMID 38236327, 2024). "However, the detailed role of GSTM5 in cancer development remains to be explored." (PMID 23818951, 2013). "Among them, only six genes—MMP11, ANGPTL1, GSTM5, IQGAP3, UHRF1, and CCBE1—were shared across all analyzed carcinomas." (PMID 39596491, 2024). "Again, the RNA editing level of two sites, chr1:110256304 on GSTM5 and chr4:10080600 on WDR1, on ubiquitination site was significantly different among different subtypes in two cancer types." (PMID 36064557, 2022). "In the present study, GSTM5 was found to decrease cellular GSH levels and suppress cancer cell proliferation and migration." (PMID 33802702, 2021). "There are no reports on the relationship between cancer and the expression level of GSTM5." (PMID 32539715, 2020). "Therefore, we want to know whether cancer cells overexpressing GSTM5 induce resistance to anticancer drugs or not." (PMID 33802702, 2021). "None of the six genes (MMP11, ANGPTL1, GSTM5, IQGAP3, UHRF1, and CCBE1) have previously been categorized as carcinoma biomarkers collectively." (PMID 39596491, 2024). "Yet, data on the role of GSTM5, PDE6B, SGPP2, PDE1B, DGKB, and PLCG2 in cancer are still lacking." (PMID 33282950, 2020).
tumor (10 papers, 2010 to 2025). "By examining both GSTM5 expression levels and genetic variants, we aim to gain valuable insights into its role in modulating tumor response to ADT, potentially offering new therapeutic strategies for treatment resistance and improving the clinical management of advanced PC." (PMID 40868127, 2025). "Previous studies have shown that GSTM5 expression can be epigenetically regulated through promoter hypermethylation, leading to gene silencing and increased tumor aggressiveness." (PMID 40868127, 2025). "Our results revealed that the GSTM5 promoter is significantly hypermethylated in tumor samples compared to normal prostate tissue (p = 1.9 × 10−12)." (PMID 40868127, 2025). "Although our study focuses on GSTM5, it is part of the larger GST family, which includes GSTM1 and GSTM2, both of which have been implicated in tumor progression and treatment response." (PMID 40868127, 2025). "The results revealed that GSTM5 was significantly downregulated in tumor tissue compared to normal prostate tissue (p < 0.0001), suggesting a potential tumor suppressor role." (PMID 40868127, 2025). "In parallel, the reduced expression of GSTM5 in tumor tissue, along with its established involvement in oxidative stress regulation and drug metabolism, support its biological relevance in therapeutic response." (PMID 40868127, 2025). "Results showed 9 sites in GSTM5 were significantly hypermethylated in the tumor tissue compared with adjacent normal tissues." (PMID 35729618, 2022). "Among the top 36 high-significance genes (q < 0.005), GSTM5 (glutathione S transferase mu 5) (q = 0.0003) suggests the role of oxidative stress defense and detoxification in reducing tumor CNA." (PMID 34070461, 2021). "Furthermore, when patients were stratified based on tumor aggressiveness, GSTM5 expression remained consistently downregulated, with a progressive decrease as tumor aggressiveness increased." (PMID 40868127, 2025). "This suggests that epigenetic regulation through hypermethylation may contribute to GSTM5 silencing in PC, potentially promoting tumor progression and treatment resistance." (PMID 40868127, 2025). "While another site, chr1:110256304 on GSTM5, was over-editing in tumor samples." (PMID 36064557, 2022). "In addition, we found the promoter region of GSTM5 was hypermethylated in the tumor tissue compared with adjacent normal tissues, and the average methylation level of GSTM5 were moderately correlated with its expression." (PMID 35729618, 2022). "GSTM2 is known to play a tumor suppressor role, and functional characteristics that may also be shared GSTM5; therefore, the effects of GSTM1-5 on cell viability were compared by overexpressing these proteins in 5637 cells." (PMID 33802702, 2021). "Therefore, our results suggest that hypermethylation of GSTM5 promoter region might be an important mechanism of dysregulation of GSTM5 and demethylation may restore GSTM5 tumor suppressor activity." (PMID 35729618, 2022). "Additionally, GSTM5’s interaction with DNA repair mechanisms may influence activation of the NRF2 pathway, thereby impacting the tumor cell’s ability to respond to treatment-induced damage." (PMID 40868127, 2025).
GSTM5 also shares sentences with these, for which no sentence is quoted: glioblastoma (3 papers); thyroid cancer (2); acute myeloid leukemia (1); age-related macular degeneration (1); autism (1); bladder tumor (1); fatty liver disease (1); glaucoma (1); glioma (1); gynecologic cancer (1); head and neck squamous cell carcinoma (1); infection (1); Insulin resistance (1); leukemia (1); nasopharyngeal carcinoma (1); neurodegenerative disease (1); Renal cyst (1); retinal disease (1); rheumatoid arthritis (1); salivary gland cancer (1); sarcoma (1); schizophrenia (1).